ALOX5 (arachidonate 5-lipoxygenase)
Diseases named in the same sentence as ALOX5 in open-access papers (continued):
Sharing a sentence is not in itself a finding about the gene and the disease.
Sepsis (14 papers, 2012 to 2025). Sepsis is defined as life-threatening organ dysfunction caused by a dysregulated host response to infection. "We next sought to evaluate the impact of using AGER inhibitor FPS-ZM1 or ALOX5 inhibitor zileuton in the development of caspase-11-associated sepsis." (PMID 31440260, 2019). "ALOX5 can be used as a potential diagnostic biomarker or therapeutic target in sepsis." (PMID 40426888, 2025). "ALOX5 was an important enzyme for producing leukotrienes (LTs) to cause lung damage in sepsis." (PMID 33949285, 2021). "ALOX5, a marker gene highly expressed in this monocyte group, was also identified in our study, suggesting its potential for classifying sepsis patients from those with sterile inflammation." (PMID 39716214, 2024). "The potent chemoattractant and proinflammatory mediator LTB4 is synthesized from arachidonic acid by ALOX5.Multiple risk factors for ARC such as trauma, sepsis, cancer, etc., also found differences in LTB4R expression." (PMID 37445637, 2023). "Here, we further showed that AGER promotes caspase-11 inflammasome activation by modulating ALOX5-dependent lipid peroxidation in macrophages during sepsis." (PMID 31440260, 2019). "More recently, the combined COX-2 and ALOX5 inhibitor flavocoxid has shown significant efficacy in a mouse cecal ligation and puncture model of sepsis." (PMID 23036193, 2012). "ALOX5 products could induce pulmonary inflammation and its inhibition attenuated sepsis-induced lung injury." (PMID 33949285, 2021). "We also observed a three-fold difference in the expression of ALOX5, a key component in the metabolism of leukotrienes that has been shown in mouse knockout models to worsen sepsis-induced multiple organ injury, and that is also mediated by glucocorticoid activity." (PMID 23036193, 2012). "Additional genes upregulated in sepsis include adrenomedullin (ADM), IRAK3, and arachidonate 5-lipoxygenase (ALOX5/5-LOX)." (PMID 41293242, 2025). "The importance of specific lipid and cholesterol metabolism genes including PCSK9, ALOX5, CETP, and DHCR7 in sepsis have been observed." (PMID 39716214, 2024). "Sepsis increased the expression of GPx (p < 0.01), GSR (p < 0.001) and Alox5 (p < 0.05) and decreased SOD-1 (p < 0.001) mRNA in the skeletal muscle." (PMID 35795581, 2022). "Pretreatment with the nutraceutical prevented the effects of sepsis on GPx and Alox-5 (p < 0.05 for both), but not on GSR and SOD-1 mRNA levels." (PMID 35795581, 2022).
myocardial infarction (13 papers, 2013 to 2025). Gross necrosis of the myocardium, as a result of interruption of the blood supply to the area, as in coronary thrombosis. "Aging in ALOX5-deficient mice causes macrophage dysfunction with an increased proinflammatory phenotype, downregulation of the formyl peptide receptor type 2 (FPR2) in the heart after myocardial infarction." (PMID 36011386, 2022). "Analysis of human blood sample sequencing datasets and mouse myocardial infarction sequencing datasets as well as cardiomyocyte hypoxia experiments indicated that FRGs ALOX5, CAMKK2, KDM6B, LAMP2, PTEN, PTGS2, and ULK1 may be potential biomarkers of AMI." (PMID 36407421, 2022). "Genetic variation in the genes ALOX5 (arachidonate 5-lipoxygenase), ALOX5AP (arachidonate 5-lipoxygenase-activating protein) and LTA4H (leukotriene A4 hydrolase) has previously been shown to contribute to the risk of MI (myocardial infarction) in Caucasian and African American populations." (PMID 30678701, 2019). "In line with this, the endogenous expression of the enzyme arachidonate 5-lipoxygenase (ALOX5), involved in the synthesis of SPMs, was found to be essential in containing the damage occurring upon myocardial infarct." (PMID 36793548, 2022).
gastric cancer (12 papers, 2011 to 2025). A primary or metastatic malignant neoplasm involving the stomach. "ALOX5 overexpression in gastric cancer cells was associated with reduced drug activity, and genetic or pharmacological ALOX5 inhibition increased drug efficacy." (PMID 36839749, 2023). "As chemoresistance is the cause of treatment failure in gastric cancer patients, a significant finding of our work reveals that ALOX5 activation alleviates toxicity induced by chemotherapy." (PMID 34121352, 2021). "While similar mechanisms have not been fully established in solid tumors, our findings that ALOX5 upregulation enhances gastric cancer stemness markers and sphere formation suggest a comparable role in maintaining CSC-like phenotypes." (PMID 41184226, 2025). "JMJD3 drives the demethylation of the ALOX5 promoter, leading to its overexpression, which helps maintain gastric cancer stem cell properties and chemoresistance." (PMID 41184226, 2025). "On the other hand, ALOX5 inhibition augments the efficacy of other chemotherapeutic agents in the treatment of gastric cancer." (PMID 35444656, 2022). "In gastric cancer and hepatocellular carcinoma, ALOX5 expression was significantly higher than that in normal tissues in the promotion of tumor progression." (PMID 35444656, 2022). "We further reveal the pro‐proliferative role of ALOX5 in gastric cancer via multiple approaches including ALOX5 overexpression, addition of 5‐HETE, genetic inhibition of ALOX5, and pharmacological inhibition of ALOX5." (PMID 34121352, 2021). "To investigate the possible role of Alox5 in gastric cancer, we performed gain‐of‐function analysis by overexpressing ALOX5 in N87 and AGS." (PMID 34121352, 2021). "In this study, we analyzed the expression, biological function and the downstream signaling of Alox5 in gastric cancer." (PMID 34121352, 2021). "Here, our work suggests that ALOX5 is an attractive therapeutic target to sensitize gastric cancer cells to chemotherapy." (PMID 34121352, 2021). "Functional analysis showed that ALOX5 overexpression increased gastric cancer proliferation as well as colony formation by 2‐ to 3‐fold." (PMID 34121352, 2021). "Our results demonstrate that the ALOX5‐5‐HETE axis promotes gastric cancer growth and alleviates chemotherapy toxicity via MEK/ERK activation." (PMID 34121352, 2021). "Gastric cancer cells display time‐dependent and dose‐dependent elevation of ALOX5 after nicotine exposure." (PMID 34121352, 2021). "To confirm the role of Alox5 in gastric cancer proliferation and responsiveness to chemotherapy, we performed loss‐of‐function analysis by depleting ALOX5 using siRNA." (PMID 34121352, 2021). "ALOX5 overexpression or 5‐HETE addition activates gastric cancer cells and reduces chemotherapy’s efficacy." (PMID 34121352, 2021). "Of note, the regulation of ALOX5 was observed in gastric cancer patients and ALOX5 expression pattern matches the 5‐HETE level." (PMID 34121352, 2021). "In contrast, ALOX5 inhibition via genetic and pharmacological approaches suppresses gastric cancer cells and enhances chemotherapy’s efficacy." (PMID 34121352, 2021). "To determine the effect of ALOX5 knockdown on gastric cancer cell responsiveness to chemotherapy, we exposed control and ALOX5 knockdown cells to chemotherapeutic agents at sublethal concentration." (PMID 34121352, 2021). "In conclusion, using multiple approaches, our work is the first to show that the ALOX5‐5‐HETE axis promotes gastric cancer growth and alleviates chemotherapy toxicity via MEK/ERK activation." (PMID 34121352, 2021). "Alox5 activation is required for nicotine‐mediated epithelial‐mesenchymal transition and gastric cancer cell growth." (PMID 34121352, 2021). "N87 and AGS were selected to demonstrate the biological role of ALOX5 because (a) these are commonly used gastric cancer cell lines for in vitro gastric cancer model; and (b) they represent different cellular origins and genetic profiles." (PMID 34121352, 2021).
gastric cancer (continued). "We observed the decreased phosphorylation of ERK and its downstream effector p90RSK in ALOX5‐depleted N87 cells, indicating that Alox5 inhibition suppresses the MEK/ERK pathway in gastric cancer cells." (PMID 34121352, 2021). "Our findings indicate that chemoresistant gastric cancer with ALOX5 overexpression may be targeted for induction of ferroptosis." (PMID 41184226, 2025). "However, the ALOX5 upregulation concomitantly renders gastric cancer sensitive to ferroptosis inducers." (PMID 41184226, 2025). "IHC analysis also revealed elevated ALOX5 expression in gastric cancer tissues." (PMID 41184226, 2025). "In addition, Alox5 inhibition led to suppression of ERK‐mediated signaling pathways whereas ALOX5‐5‐HETE activates ERK‐mediated signaling in gastric cancer cells." (PMID 34121352, 2021). "Similarly, we found that the average Alox5 protein level was significantly higher in gastric cancer tissues compared with adjacent normal counterparts." (PMID 34121352, 2021). "Our findings emphasize the therapeutic value of ALOX5 inhibition in gastric cancer." (PMID 34121352, 2021). "Our work demonstrates that the ALOX5‐5‐HETE axis promotes gastric cancer growth and alleviates chemotherapy toxicity via MEK/ERK activation and provides pre‐clinical evidence to initialize clinical trials using zileuton in combination with chemotherapy for the treatment of gastric cancer." (PMID 34121352, 2021). "It is interesting to compare ALOX5 expression levels in smokers and non‐smokers with gastric cancer to understand whether ALOX5 level in gastric cancer is regulated by carcinogenic agents." (PMID 34121352, 2021). "Our work extends the previous findings by suggesting that (a) ALOX5 upregulation is a common molecular feature in gastrointestinal tract cancers; (b) ALOX5 expression is heterogeneous in gastric cancer patients; and (c) activation of ALOX5‐5‐HETE axis in gastric cancer." (PMID 34121352, 2021). "Scatter plot from ELISA analysis showed that the average Alox5 protein level is upregulated in gastric cancer tissues compared to their corresponding normal counterparts, and furthermore, the upregulation is regardless of patients’ clinicopathological features." (PMID 34121352, 2021). "MK886 blocked the ERK/ALOX5 pathway to induce apoptosis in human gastric cancer cells." (PMID 31871543, 2019). "We next assessed the 5‐HETE level to determine whether Alox5 was active in gastric cancer." (PMID 34121352, 2021). "In addition, ALOX5 inhibition augments chemotherapeutic agents’ efficacy in gastric cancer." (PMID 34121352, 2021). "Altogether, our results demonstrate that the Alox5‐5‐HETE signaling axis is upregulated and activated in gastric cancer." (PMID 34121352, 2021). "In this work, we analyzed the levels of ALOX5 and 5‐HETE on tumor tissues and corresponding normal counterparts from gastric cancer patients using quantitative and qualitative methods." (PMID 34121352, 2021). "In contrast, ALOX5 overexpression and addition of 5‐HETE increased p‐ERK and p‐p90RSK, demonstrating the activation of ERK in gastric cancer cells." (PMID 34121352, 2021). "To assess whether ALOX5 mediates the oncogenic role of JMJD3 in gastric cancer tumorigenesis, we first investigated if the oncogenic effect of JMJD3 overexpression could be attenuated through ALOX5 depletion." (PMID 41184226, 2025). "Alox5 and 5‐HETE levels were upregulated in gastric cancer patients." (PMID 34121352, 2021). "Consistently, Alox5 specific inhibitors zileuton and 2,3,5‐trimethyl‐6‐(12‐hydroxy‐5,10‐dodecadiynyl)‐1,4‐benzoquinone (AA861), significantly inhibited proliferation and induced apoptosis of gastric cancer cells." (PMID 34121352, 2021). "Our work demonstrates the critical role of ALOX5‐5‐HETE in gastric cancer and provides pre‐clinical evidence to initialize clinical trial using zileuton in combination with chemotherapy for treating gastric cancer." (PMID 34121352, 2021).
gastric cancer (continued). "However, the expression, biological function, and downstream signaling mechanism of ALOX5 in gastric cancer have not been systematically evaluated." (PMID 34121352, 2021). "In contrast, ALOX5 overexpression did not affect gastric cancer migration." (PMID 34121352, 2021). "In addition, the ALOX5‐5‐HETE axis is not involved in gastric cancer cell migration." (PMID 34121352, 2021).
Stroke (11 papers, 2006 to 2025). Sudden impairment of blood flow to a part of the brain due to occlusion or rupture of an artery to the brain. "Specifically, PPARα KO led to increased expression levels of Gadd45b, Nppa, Hdc, Lcn2, Il6, Sox4, Marcksl1, Saa3, Ucn2, Met, Dusp10, Elovl7, Ngf, C3, Il11, Hmox1, Alox5, Tnfsf9, Angptl4, Plin2, H19, Csf2rb, Atf3, and Col7a1 following stroke." (PMID 40362325, 2025). "In human atherosclerotic plaques, constituents of the ALOX5 pathway are expressed at high levels in patients suffering from a stroke, compared to asymptomatic patients." (PMID 24475136, 2014). "Pharmacological repression of ALOX5 protected neurons from ferroptosis in mice with stroke." (PMID 34447410, 2021).
Arthritis (10 papers, 2009 to 2026). Inflammation of a joint. "Future studies should employ macrophage-specific ALOX5 knockout or celastrol treatment in collagen-induced arthritis models to directly validate the proposed ALOX5–macrophage–NF-κB axis and its role in bone destruction." (PMID 41408107, 2025).
bladder cancer (10 papers, 2020 to 2025). "Meanwhile, ALOX5 may be a valuable therapeutic target and prognostic biomarker for bladder cancer, in which the deficiency of ALOX5 might contribute to BCa progression by mediating ferroptosis escape." (PMID 40761790, 2025). "EGR1-regulated ALOX5 deficiency can promote ferroptosis resistance in bladder cancer." (PMID 39544949, 2024). "On the contrary, ALOX5 knockout contributes to bladder cancer development by mediating escape from ferroptosis." (PMID 38612771, 2024). "Deoxyschizandrin inhibits the proliferation, migration, and invasion of bladder cancer cells through ALOX5 regulating PI3K-AKT signaling pathway." (PMID 35664354, 2022). "In a more recent study, overexpression of ALOX5 sensitizes bladder cancer cells to ferroptosis." (PMID 38612771, 2024). "In order to study whether Deoxyschizandrin can regulate the expression of ALOX5, bladder cancer cells were treated with 5, 10, and 50 μmol/L Deoxyschizandrin." (PMID 35664354, 2022). "The present study identified ALOX5 as a target gene, further implying that bladder cancer may benefit from novel ferroptosis-related treatments." (PMID 34095228, 2021). "Importantly, previous studies have identified ALOX5 as a key mediator of ferroptosis in various cancers, including melanoma and bladder cancer, suggesting that ALOX5 expression may serve as an indicator of susceptibility to ferroptosis." (PMID 41184226, 2025). "Then, the expressions of ALOX5 and PI3K-AKT signaling pathway proteins were detected by Western blot in bladder cancer cells treated with Deoxyschizandrin." (PMID 35664354, 2022).
ovarian carcinoma (10 papers, 2019 to 2025). A malignant neoplasm originating from the surface ovarian epithelium. "ALOX enzymes are involved in xenobiotic and drug metabolism, with ALOX5 overexpression linked to cell metastasis in ovarian cancer." (PMID 39997761, 2025). "Inherited variation in ALOX5 seems to affect ovarian cancer risk." (PMID 38178187, 2024).
Allergy (9 papers, 2008 to 2026). An allergy is an immune response or reaction to substances that are usually not harmful. "This study aimed to investigate whether two SNPs of ALOX5 are implicated in sex differences in allergic diseases in a prospective cohort of 150 age- and sex-matched atopic and healthy subjects." (PMID 37109111, 2023). "Therefore, the aim of this study was to assess whether two genetic variations of the ALOX5 gene, rs2029253 and rs2115819, are implicated in the sex difference in allergic diseases in a well-characterized patient cohort of both atopic and healthy subjects." (PMID 37109111, 2023). "Gene expression studies of MS and EAE lesions have also reported increased levels of ALOX5 in addition to other allergy-related mediators." (PMID 18366677, 2008).
colitis (9 papers, 2014 to 2025). Inflammation of the colon. "Consistent with the results from in vitro experiments, we observed a reduction in the expression of Gpx4, while Acsl4 and Alox5 were upregulated in the DSS‐induced colitis model at the transcription level." (PMID 38340032, 2024). "In conclusion, our study demonstrated that a non‐cytotoxic dose of magnolin effectively alleviated DSS‐induced colitis attributed to its inhibition of ferroptosis‐related ALOX5, inflammation reduction, and regulation of macrophage polarization." (PMID 38340032, 2024). "Our findings demonstrated that magnolin effectively ameliorated colitis by mitigating ALOX5‐mediated ferroptosis in IECs and concurrently suppressing pro‐inflammatory cytokine production." (PMID 38340032, 2024). "DSS–colitis experiments with Alox5−/− mice in connection with lipidomic analyses would help to answer this question." (PMID 37446212, 2023). "The limited protective effect we observed for our Alox5-KI mice in the DSS colitis model was somewhat surprising since the ALOX5 inhibitor zileuton protected animals in different models of inflammatory bowel disease." (PMID 34677413, 2021). "When we induced DSS colitis in our Alox5-KI mice and wildtype controls we only observed a minor difference between the two genotypes." (PMID 34677413, 2021). "Previous experiments with the clinically used ALOX5 inhibitor zileuton suggested that inactivation of endogenous leukotriene biosynthesis attenuated the inflammatory symptoms in different animal colitis models." (PMID 34677413, 2021). "Consistent with this, the BN suggests that HCK regulates ALOX5, whose absence has a protective role in an experimental mouse model of colitis." (PMID 32565911, 2020). "Moreover, we found that the expression of ALOX5 was upregulated in patients and experimental colitis models." (PMID 38340032, 2024). "Experiments with the specific ALOX5 inhibitor (zileuton) in different murine colitis models have indicated that interference with endogenous leukotriene biosynthesis protected the animals from colitis development." (PMID 34677413, 2021). "In dextran sodium sulfate-induced colitis (DSS) and in the chronic constriction nerve injury model (CCI), Alox5-KI mice performed like wildtype controls with similar genetic background." (PMID 34677413, 2021). "We found that in the experimental autoimmune encephalomyelitis (EAE) model and in the dextran sodium sulfate induced colitis (DSS) model, Alox5-KI mice showed different responses than other leukotriene-deficient animals explored in the literature." (PMID 34677413, 2021). "In two other animal inflammation models (DSS colitis model, CCI model of neuropathic pain) the Alox5-KI mice behaved like wildtype control animals." (PMID 34677413, 2021). "Since our Alox5-KI mice were unable to biosynthesize leukotrienes, it was expected that these animals should also be protected from DSS-induced colitis." (PMID 34677413, 2021). "For most clinical readout parameters of colitis severity (body weight kinetics, colon shortening, DAI), we did not observe significant differences between Alox5-KI mice and wildtype controls." (PMID 34677413, 2021).
hepatocellular carcinoma (9 papers, 2012 to 2025). A malignant tumor that arises from hepatocytes. "Expression of ALOX5 steadily increases with the progression of human Hepatocellular Carcinoma in HepG2 cells and- inhibition of ALOX5 via zileuton administration decreased cell viability and induced apoptosis in HepG2 cells." (PMID 38612771, 2024).